FGFR4 (fibroblast growth factor receptor 4)
Diseases named in the same sentence as FGFR4 in open-access papers (continued):
Sharing a sentence is not in itself a finding about the gene and the disease.
cardiac hypertrophy (continued). "We have previously shown that administration of anti-FGFR4 prevents the development of LVH in the 5/6 nephrectomy rat model of CKD11, indicating that FGF23/FGFR4 is important for the initiation of cardiac hypertrophy in the context of kidney injury." (PMID 28512310, 2017). "In the CKD milieu, FGF23 induces cardiac hypertrophy that is accompanied by pathologic alterations, while by itself FGF23/FGFR4 signaling causes hypertrophy that might be beneficial." (PMID 39452290, 2024). "In addition, the increase in concentricity index at endpoint in db/db mice, indicative of concentric cardiac hypertrophy, was prevented by treatment with the FGFR4 antibody." (PMID 35513431, 2022). "It is reported that FGF23 induces cardiac hypertrophy by Klotho-independent binding to FGFR4." (PMID 34765890, 2021). "This FGFR4-mediated effect may play a key role in cardiac hypertrophy through FGFR4 during highly elevated FGF23 in CKD." (PMID 32982979, 2020). "This supports the hypothesis that phosphate promotes LVH by stimulating FGF23, which is known to induce cardiac hypertrophy via FGFR4." (PMID 31698866, 2019). "Instead, the cardiac myocyte-specific deletion of the FGF23 receptor, i.e., FGFR4, followed by the elevation of circulating FGF23 should help to determine whether direct cardiac actions of FGF23/FGFR4 contribute to cardiac hypertrophy." (PMID 29770125, 2018). "Taken together, our data suggest that the well-established cardiac FGF23/FGFR4 signaling involved in the development of pathologic cardiac hypertrophy with the parallel appearance of cardiac fibrosis is induced in kl/kl mice with high FGF23 levels and klotho deficiency." (PMID 29977226, 2018). "Animal models with elevated serum FGF23 levels, induced by CKD, genetic deletion of klotho, injection of recombinant FGF23 protein, or a high phosphate diet, develop cardiac hypertrophy, which can be blocked by administration of specific inhibitors for FGFR4 or calcineurin." (PMID 29770125, 2018). "Our findings suggest that FGF23 acutely increases intracellular calcium levels and cardiac contractility, but that sustained activation of cardiac FGFR4 might induce changes that progress to pathologic remodeling including cardiac hypertrophy and fibrosis." (PMID 28512310, 2017). "The increase of FGFR4 expression in the heart of the CRS mice maybe attributable to the compensatory myocardial hypertrophy induced by MI and the upregulation of its ligand FGF23, and the similar phenomenon has been reported from both experimental and clinical investigations." (PMID 33460402, 2021). "The phosphate-induced cardiac hypertrophy could be prevented by a global knockout of FGFR4." (PMID 31698866, 2019). "Furthermore, to determine whether circulating FGF23 might contribute to physiologic cardiac hypertrophy requires studies in animals with genetic modifications of the FGF23/FGFR4 signaling pathway in the heart." (PMID 29770125, 2018). "Furthermore, studies in a rat model of CKD have shown that administration of a FGFR4-specific blocking antibody (anti-FGFR4) not only prevents the induction of cardiac hypertrophy, but also blocks the progression of cardiac injury in animals with already established cardiac hypertrophy." (PMID 29770125, 2018). "Several previous studies have suggested that FGF23 may promote cardiac hypertrophy via FGF receptor 4 (FGFR4)-mediated activation of the calcineurin-NFAT signaling pathway, although to what extent circulating FGF23 reflects myocardial FGF23 in the setting of heart failure remains under discussion." (PMID 27400031, 2016). "Studies have demonstrated that increased levels of FGFR4 are correlated, in CKD, with ventricular hypertrophy, atrial fibrillation, fluid overload and HF." (PMID 41375859, 2025). "FGF23 activates fibroblast growth factor receptor 4 (FGFR4) phospholipase Cγ/calcineurin/nuclear factor of activated T cells signaling in cardiomyocytes and leads to cardiac hypertrophy and myocardial fibrosis in rodents." (PMID 38124483, 2024).
cardiac hypertrophy (continued). "FGF23 induces hypertrophic growth of cultured cardiac myocytes via FGFR4, and deletion or blockade of FGFR4 in CKD rodent models with elevated FGF23 protects from cardiac hypertrophy." (PMID 39452290, 2024). "Experimental studies have shown that FGF23 activates fibroblast growth factor receptor 4 (FGFR4)/phospholipase Cγ/calcineurin/nuclear factor of activated T-cells signaling in cardiomyocytes and induces cardiac hypertrophy in rodents." (PMID 36909314, 2023). "FGF23 activates FGFR4/phospholipase Cγ/calcineurin/nuclear factor of activated T-cells (NFAT) signaling in cardiomyocytes and induces cardiac hypertrophy in rodents." (PMID 36909314, 2023). "For example, FGF-23 regulates cardiac hypertrophy by acting directly on FGF receptor 4 (FGFR4), while FGFR4 activation requires klotho as a cofactor." (PMID 36132198, 2022). "To determine whether FGF23/FGFR4 contributes to physiologic cardiac hypertrophy, we studied FGFR4 knockout mice (FGFR4−/−) during late pregnancy." (PMID 39452290, 2024). "Thus, leading to the conclusion that beside FGFR4/PLCγ/calcineurin signaling pathway, FGF23 promotes cardiac hypertrophy and fibrosis via activation of intra-cardiac RAAS." (PMID 34422725, 2021). "On the other hand, experimental studies showed that, even on a high phosphate diet, cardiac hypertrophy does not occur when FGFR4 is blocked." (PMID 34065339, 2021). "FGF23 directly targets cardiac myocytes via the described FGFR4/PLCγ/calcineurin/NFAT signaling pathway and induces cardiac hypertrophy, and potentially other changes in cardiac remodeling, including cardiac fibrosis and altered cardiac metabolism, eventually resulting in reduced heart function." (PMID 29770125, 2018). "First, we use pregnant FGFR4−/− mice to demonstrate that increased width, or concentric growth, of individual cardiac myocytes in pregnancy-induced physiologic cardiac hypertrophy is dependent on FGFR4, but that this mechanism does not affect the hypertrophic increase in heart mass." (PMID 39452290, 2024). "Though these studies have focused on pathologic hypertrophy, the significant elevation of FGF23 over the course of exercise training and pregnancy suggests that FGF23/FGFR4 signaling could play a role in physiologic cardiac hypertrophy as well, which is supported by our study." (PMID 39452290, 2024). "A retrospective study with autopsy samples from heart tissue of 24 deceased pediatric patients showed that only individuals who had developed cardiac hypertrophy also showed significant elevations of FGFR4 in the heart, but not of FGFR1, as well as of calcineurin and NFAT." (PMID 29770125, 2018). "These lines of evidence suggest that FGF23-induced cardiac hypertrophy is reversible in vitro and in vivo, following the removal of hypertrophic stimulus, and indicate that pharmacological interference with cardiac FGF23/FGFR4 signaling might provide protection from CKD- and age-related LVH." (PMID 33000285, 2021). "Our study suggests that in physiologic cardiac hypertrophy, the heart produces FGF23 that contributes to hypertrophic growth of cardiac myocytes in a paracrine and FGFR4-dependent manner, and that the kidney does not respond to heart-derived FGF23." (PMID 39452290, 2024). "In the current study, the relationship between FGF23 and cardiac hypertrophy differed according to CKD stage; therefore, whether or not differences between the various CKD stages might be explained by variations in the cardiac expression of FGFR4 awaits further investigation." (PMID 27400031, 2016).
colon cancer (24 papers, 2011 to 2025). "The c.1162G > A (p.Gly388Arg) variant in FGFR4 gene, and the increase in the FGFR4 expression were associated with the development of breast, and colon cancer." (PMID 31207142, 2019). "Moreover, further analysis of data from patients with colon adenocarcinoma in TCGA dataset revealed associations of increased FGFR4 expression levels with the occurrence, advanced stage, and distal metastasis of colon cancer." (PMID 34071523, 2021). "We previously reported the role of FGFR4 in EMT induction and the mechanism underlying anti-EGFR chemoresistance based on amphiregulin secretion in colon cancer." (PMID 40447617, 2025). "Our current data demonstrate that FGFR4 induces CXCL10 production in colon cancer cells and that the secreted CXCL10 promotes CAF differentiation in a paracrine manner." (PMID 40447617, 2025). "To investigate the impact of FGFR4 overexpression on tumor growth and CAF activation, we established a subcutaneous tumor model using mouse colon cancer CT-26/EV or CT-26/FGFR4 stable-expressing cell lines." (PMID 40447617, 2025). "Clinical samples of colon cancer patients were evaluated to assess the correlation between the expression of FGFR4, CXCL10, and CAF markers." (PMID 40447617, 2025). "In human colon cancer samples, FGFR4 and CXCL10 expression was positively correlated with CAF marker expression." (PMID 40447617, 2025). "Elevated FGFR4 expression levels contribute to the occurrence of colon cancer and an inclination to develop late-staged tumors and distant metastasis." (PMID 34071523, 2021). "Blocking either FGF19 or FGFR4 significantly reduces in vivo xenograft tumor growth of colon cancer cells." (PMID 32154250, 2020). "Further, a previous study of colon cancer shows activation of the EGFR signaling pathway through fibroblast growth factor receptor 4 (FGFR4), a tyrosine kinase." (PMID 33037736, 2020). "In vitro, knockdown of FGFR4 suppresses colon cancer cell proliferation and migration, again indicating that FGFR4 is a promising therapeutic target in colon cancer." (PMID 32154250, 2020). "Fibroblast growth factor receptor 4 (FGFR4) was found to be highly expressed in colon cancers and to induce drug resistance." (PMID 27384995, 2016). "The use of specific antibodies for FGFR4 inhibition also showed a neutralizing effect on colon cancer cells that confirmed the specificity of the inhibition." (PMID 23696849, 2013). "We demonstrated that FGFR4 suppression reduces significantly the levels of TWIST in colon cancer cells, more than those of SNAIL." (PMID 23696849, 2013). "There was evidence that FGFR4 contributed to progression in liver, lung, colon tumors and prostate cancer." (PMID 21349172, 2011). "In this study, we investigated the role of FGFR4 in CAF regulation in colon cancer." (PMID 40447617, 2025). "In this study, we explored whether FGFR4 signaling induces CAF differentiation and the underlying mechanism to provide new insights for exploring CAF-targeted therapies in colon cancer." (PMID 40447617, 2025). "The depletion of FGFR4 suppresses the proliferation and migration of colon cancer cells." (PMID 38540215, 2024). "Similarly, in colon cancer, overexpression of FGFR4 triggers AREG secretion, which promotes tumor growth through EGFR phosphorylation at Tyr1068." (PMID 39451251, 2024). "Furthermore, we observed mutations affecting FGFR4, KLC1 and XRCC3, associated to colon cancer and melanoma." (PMID 35836575, 2022). "Another study in human colon cancer cell lines indicates that when FGF19 interacts with its receptor FGFR4, there is an increase in phosphorylated glycogen synthase kinase 3β (GSK3β), an intermediary of Wnt pathway, which actives β-catenin, that, in turn, causes loss of β-catenin-E-cadherin binding." (PMID 34200439, 2021). "FGFR4 has also been demonstrated to be a poor prognostic indicator in colon cancer." (PMID 34540690, 2021). "FOXC1 also transcriptionally upregulates FGFR4 in colon cancer." (PMID 34540690, 2021).
colon cancer (continued). "As earlier discussed, FOXC1 transcriptionally upregulates FGFR4 in colon cancer." (PMID 34540690, 2021). "Hyperactivation of FGFR4 by FGF19 was reported in colon cancer cells and hepatocellar carcinoma." (PMID 32154250, 2020). "Additionally, other studies have suggested that FGFR4 knockdown leads to slower tumor progression in a rodent model of colon cancer." (PMID 31408968, 2019). "In another investigation focused on FGFR4 missense variant, the GG of FGFR4 rs351855 (Gly 388 Arg) showed significantly better overall survival than the AG or AA among 273 colon cancer patients, regardless of adjuvant treatment." (PMID 30359238, 2018). "In summary, we have demonstrated a potent oncogenic activity of FGFR4 in colon cancer cells." (PMID 23696849, 2013). "Together, these results indicate that targeting of FGFR4 might become a potent therapeutic tool in colon cancer." (PMID 23696849, 2013). "In addition, rs351855 may act as an eQTL for FGFR4 gene expression, which correlated with the onset, advancement, and metastasis of colon cancer." (PMID 34071523, 2021). "The expression levels of FGFR4, CXCL10, and CAF markers were significantly upregulated in colon cancer tissues compared with those in normal tissue samples." (PMID 40447617, 2025). "Evidence suggests that intestinal epithelial cells express receptors that recognize FGF19, such as FGFR4 and β-Klotho, and cultured mouse enteroids respond to FGF19 treatment and inhibition of FGF19 reduced growth and metastasis of colon tumor grafts." (PMID 41043692, 2025). "There is evidence in human colon cancer cell lines, colon tumor xenografts, and FGF19 transgenic mice that blocking selectively the interaction of FGF19 and FGFR4 using an anti-FGF19 monoclonal antibody has a potential pharmacological anti-tumorigenic effect." (PMID 34200439, 2021). "Activation of β-catenin through the FGF19/FGFR4 system has been thoroughly characterized in human HCC and colon cancer cells." (PMID 23285165, 2012). "In conclusion, FGFR4 in cancer cells promotes CXCL10 production via TLR3-IRF-IFNβ-dependent signaling that subsequently induces CAF differentiation and activation, culminating in colon cancer progression." (PMID 40447617, 2025). "In addition, activated FGFR4 stimulates AKT, ERK1/2, and Src, promoting the invasive activity of colon cancer (CRC) cells." (PMID 32154250, 2020). "In addition, FGFR4-signaling activated the oncogenic SRC, ERK1/2 and AKT pathways in colon cancer cells and promoted an increase in cell survival." (PMID 23696849, 2013). "Then, these data suggest that the increased expression of FGFR4 could be responsible for autoantibody induction in CRC patients and higher invasion and metastasis in colon cancer." (PMID 23696849, 2013). "FGFR4 expression was significantly positively correlated with that of CXCL10 (Pearson’s R = 0.32; P < 0.001) and CAF markers, including α-SMA (Pearson’s R = 0.43; P < 0.0001), PDGFR-β (Pearson’s R = 0.46; P < 0.0001), and FAP (Pearson’s R = 0.32; P < 0.001) in colon cancer samples." (PMID 40447617, 2025).
prostate carcinoma (24 papers, 2003 to 2025). A carcinoma that arises from epithelial cells of the prostate gland. "A common germline polymorphism (FGFR4:c.1162G > A) has been associated with an increased risk of developing breast and prostate cancers." (PMID 32357859, 2020). "FGFR4 rs2011077 with the GG genotype also increased the risk of prostate cancer in Japanese population." (PMID 33017009, 2020). "The expression of FGFR4 was markedly increased in prostate cancer and was associated with higher Gleason score and worse outcomes." (PMID 32154250, 2020). "FGFR4 transmembrane domain polymorphism (FGFR4 Gly388Arg) has been reported to be associated with increased risks of breast and prostate cancer in Asian population." (PMID 32154250, 2020). "The variant in the gene FGFR4 was effective in the initiation, and in the progression of prostate cancer (Wang, Stockton, & Ittmann, 2004)." (PMID 31207142, 2019). "The previous study showed that overexpression of FGFR4 is significantly associated with a high clinical stage and tumor grade as well as poor patient survival in prostate cancer." (PMID 29221201, 2017). "Several polymorphisms of FGFR4 are associated with the incidence and mortality of numerous cancers, including prostate cancer." (PMID 27640814, 2016). "Three common polymorphisms (rs1966265, rs2011077, and rs351855) of FGFR4 were genotyped from 346 patients with prostate cancer by using the Sequenom MassARRAY system." (PMID 27640814, 2016). "In this study, three common polymorphisms of FGFR4 were successfully genotyped in 346 patients with clinically localized prostate cancer." (PMID 27640814, 2016). "In this study, we analyzed several common polymorphisms of FGFR4 in 346 Chinese men with clinically localized prostate cancer and investigated the prognostic role of these genetic variants in biochemical recurrence (BCR) after radical prostatectomy." (PMID 27640814, 2016). "To date, several groups have also evaluated the association between FGFR4 polymorphisms and prostate cancer prognosis, but their results are inconsistent." (PMID 27640814, 2016). "The underlying biological association between FGFR4 polymorphisms and prostate cancer has attracted extensive attention and several mechanisms have been proposed." (PMID 27640814, 2016). "The results indicated that FGFR4 Arg388 allele is a potential risk factor for developing and progressing prostate cancer." (PMID 21349172, 2011). "Overall, four articles (six studies) with 2618 prostate cancer cases and 2305 controls were retrieved based on the search criteria for prostate cancer susceptibility related to the FGFR4 Gly388Arg polymorphism." (PMID 21349172, 2011). "The present meta-analysis, including 2,618 cases and 2,305 controls from six published studies, explored the association between FGFR4 Gly388Arg polymorphism and development and progression of prostate cancer." (PMID 21349172, 2011). "Gly388Arg polymorphism in FGFR4 gene has been reported to be involved in prostate cancer incidence and aggressiveness in several studies." (PMID 21349172, 2011). "Members of the FGFR family of receptor tyrosine kinases are of tremendous significance in many aspects of normal development and, additionally, have been implicated in a variety of human cancers, such as FGFR4 with regards to prostate cancer." (PMID 21203561, 2010). "The FGFR4 Gly388Arg variant has been statistically proved to be related to poor survival, increased cancer susceptibility and nodal involvement, especially in breast and prostate cancer." (PMID 35701820, 2022). "In summary, this meta-analysis revealed that FGFR4 rs351855 (Gly388Arg) polymorphism might be a marker for susceptibility to prostate cancer." (PMID 33017009, 2020). "Although genetic and ethnic factors may play an important role in the development of prostate cancer, the effect of the polymorphisms of FGFR4 on other racial populations with prostate cancer remains to be clarified." (PMID 27640814, 2016).